IL5 (interleukin 5)
Diseases named in the same sentence as IL5 in open-access papers (continued):
Sharing a sentence is not in itself a finding about the gene and the disease.
COVID-19 (continued). "Increased levels of interleukins (IL-1 α, IL-7, IL-17, and IL-18) and chemokines (CCL11, and CXCL1) were found only in the COVID-19-only, whilst PLWH/COVID-19, had increased levels of four different interleukins (IL-5, IL-6, IL-9, and IL-15) and one chemokine (CXCL10) compared to COVID-19-only." (PMID 41516165, 2025). "In addition, our group has previously shown that the PBMC from patients with COVID-19 activated with mixed antigens from SARS-CoV-2 produce more IL-5 in the severe COVID-19 population." (PMID 40710346, 2025). "The cytokine storms are characterized by significant induction of specific cytokines such as IL-6, IL-2, IL-7, GM-CSF, and IFN-γ in COVID-19 patients, which are different from other respiratory viruses with the increase in cytokines such as IL-2, IL-10, IL-4, or IL-5." (PMID 41002992, 2025). "It has been reported in some studies that patients with severe COVID-19 have increased IL-5 levels." (PMID 39340009, 2024). "Out of the 17 cytokines tested, nine (IL-1β, IL-2, IL-4, IL-5, IL-12, IL-13, IL-17, granulocyte colony-stimulating factor (G-CSF), granulocyte-macrophage colony-stimulating factor (GM-CSF)) were undetectable in the peripheral blood of COVID-19 patients." (PMID 39408857, 2024). "The higher median IgM, IgA, and IgG1 values in the sera of the MIS-C cohort to some of the COVID-19 Ags may relate to the higher type-2 cytokines (IL-4, IL-5, IL-6, and IL-13) and IL-21 enhanced Tfh activity known to promote B-cell activities." (PMID 38932242, 2024). "Moreover, patients with severe/critical COVID-19 showed increased levels of Th1 cytokines and decreased levels of Th2 cytokines (IL-5)." (PMID 39614276, 2024). "We noted a correlation between mepolizumab and COVID-19, which may be attributed to the inhibition of IL-5 signaling by the drug and a reduction in Th2 responses." (PMID 39574910, 2024). "Except for IL-8 decreased in the second trimester after infected with SARS-CoV-2, IL-2, TNF-α, TNF-β, IFN-γ, IL-4, IL-5, IL-6, IL-10, IL-17A, IL-17F, IL-22, IL-1β and IL-12p70 didn't change in the three trimesters between healthy pregnancies and pregnant women with COVID-19." (PMID 39113896, 2024). "IL-5 expression had an Area Under the Curve (AUC) of 0.6310 and a cutoff value of 1.70 for COVID-19 mortality, while 25(OH)D levels had an AUC of 0.661 and a cutoff value of 36.04 for COVID-19 mortality." (PMID 37705107, 2023). "Therefore, IL-5-dependent eosinophilia in CHIs can reduce COVID-19 severity through the antiviral and anti-inflammatory effects of high eosinophil counts." (PMID 37383608, 2023). "Similarly, the levels of IL-8 (P=0.005), IP-10 (P=0.035) and IL-5 (P=0.01) were higher in COVID-19 patients compared to HC." (PMID 37207201, 2023). "The serum 25(OH)D status in COVID-19 patients correlated negatively with the expression of IL-5." (PMID 37705107, 2023). "We found that, while the EPs from HC inhibit IL-5 and IL-10 production, the EPs from COVID-19 patients failed in downregulating these two cytokines, suggesting that the composition of the EPs isolated from COVID-19 patients was supporting the ILC2 activation status." (PMID 37207201, 2023). "Thus, it is possible that vitamin D reverses disease in COVID-19 patients by reducing IL-5 production." (PMID 37705107, 2023). "Altogether these data highlight that the presence of a well-known inflammatory microenvironment in severe COVID-19 patients might be reflected in more activated ILC2 producing high concentrations of both IL-5 and IL-10." (PMID 37207201, 2023). "Serum 25(OH)D levels combined with IL-5 levels and Eos counts could serve as predictors of early COVID-19-related lung injury and mortality." (PMID 37705107, 2023). "Serum 25(OH)D levels combined with IL-5 levels and Eos counts could serve as predictors of early COVID-19-related mortality." (PMID 37705107, 2023).
COVID-19 (continued). "IL-5 levels were higher in patients with vitamin D deficiency than in those with normal or insufficient vitamin D. A few studies have suggested that anti-IL-5 drugs can reverse aberrant immune responses, and thus protect infected subjects from severe COVID-19-related complications." (PMID 37705107, 2023). "It was previously shown that the lower levels of IFN-α in the blood of seriously ill COVID-19 patients could be accompanied by elevated levels of pro-inflammatory cytokines (IL-5, IL-6, IL-10, and IL-13)." (PMID 36014561, 2022). "The significant increase in IL-2 and IL-5 production by PBMCs may indicate the involvement of PBMCs in the increased IL-2 and IL-5 levels observed during the cytokine storm in COVID-19 ICU patients." (PMID 36363785, 2022). "Of note, the higher levels of Th2 cytokines, particularly IL-4 and IL-5, might inhibit Th1 protective antiviral responses in COVID-19 patients." (PMID 33995342, 2021). "A reasoned timing and appropriate patient selection in a randomized controlled clinical trial is the only way to establish whether IL-5 antagonism in COVID-19 is beneficial or harmful." (PMID 33767626, 2021). "An idea of the effect of IL-5 antagonism in severe COVID-19 may be inferred from the results of a small clinical trial that explored granulocyte-macrophage colony-stimulating factor (GM-CSF) antagonism." (PMID 33767626, 2021). "Because IL-5 is essential for the survival, maturation, and activation of eosinophils, it is suggested that IL-5 inhibitor drugs might block eosinophils activation in severe COVID-19 patients." (PMID 33767626, 2021). "Here, a rationale for anti-IL5 drug use in severe COVID-19 patients is discussed." (PMID 33767626, 2021). "However, the two studies agree with the increase of fundamentals type 2 cytokines, like IL-5 and IL-13 in severe COVID-19 patients, at least in a subset of them." (PMID 33767626, 2021). "Moreover IL-1β, IL-2, IL-5, IL-18, TNFα, and GM-CSF became detectable in all the samples following co-culture between resting PBMCs from COVID-19 patients and DPSCs." (PMID 33634100, 2020). "Interestingly, the production of cytokines by CD4+ (mainly IL-2 and IFN-γ and trace amounts of IL-4, IL-5, IL-13, or IL-17α) was also reported in COVID-19 convalescents." (PMID 32916812, 2020). "Thus, in the context of COVID-19, IL-4 and IL-5 may contribute to enhancing humoral immunity, promoting the generation of antibodies that target the SARS-CoV-2 virus." (PMID 40910046, 2025). "Interestingly, COVID-19 patients who develop severe disease have a complex maladapted immune profile that is accompanied by an increase in cytokines, such as IL-6, along with higher type-1 (e.g. IL-12) and type-2 cytokine (e.g. IL-5) levels." (PMID 37705107, 2023). "Whether vitamin D plays a protective role by regulating IL-5 in COVID-19 patients remains unknown." (PMID 37705107, 2023). "When combined with IL-5 levels and Eos counts, the predictive value was even higher, indicating the advantage of using a 25(OH)D level < 36.04 ng/mL combined with an IL-5 level > 1.70 pg/mL and an Eos count > 0.015 in place of 25(OH)D alone to predict COVID-19-related death." (PMID 37705107, 2023). "Considering that eosinophils may participate in COVID-19’s immunopathology and that anti-IL-5 drugs could be effective even starting from relatively modest levels of eosinophil counts, it is tempting to speculate that treating COVID-19 patients with such biologicals might prove beneficial." (PMID 33767626, 2021). "Furthermore, COVID-19 may causes CD8 T-cell depletion, which normally produces IL-5, amongst others." (PMID 34625911, 2021). "Thus, this study indicates that contrary to what has recently been suggested, hospitalized COVID-19 patients at risk of fatal outcomes should not be treated with anti-IL-5 drugs, such as mepolizumab." (PMID 34578258, 2021). "Pro-inflammatory cytokines, such as IL-5, IL-6, IL-9, and IL-15, were elevated in PLWH/COVID-19 compered to COVID-19-only." (PMID 41516165, 2025).
COVID-19 (continued). "Six chemokines (CXCL9, CXCL10, CCL4, CCL5, CCL27, and CXCL12) and eight interleukins (IL-1Ra, IL-2Ra, IL-3, IL-5, IL-9, IL-12p40, IL-15, and IL-16) were increased in both PLWH/COVID-19 and COVID-19-only." (PMID 41516165, 2025). "None of the other measured mediators related to eosinophils and the T2 response (CCL26, IL-3, IL-4, IL-5, CD44, TSLP, or GM-CSF) displayed any significant differences between the different timepoints and between COVID-19 versus controls." (PMID 40710346, 2025). "A closer inspection of the mRNA list unveils another interesting pattern—Th2 supporting cytokines such as IL5 and IL13 are among the most positively upregulated mRNAs in COVID-19 (+) samples." (PMID 38932146, 2024). "This classifier reinforced the prognostic importance of monocyte/macrophage, NK cell, and Th1-pathway activation, with prediction of severe COVID-19 driven by higher concentrations of IL-7, CXCL10, IL-15, and CXCL9, and lower concentrations of MDC and IL-5." (PMID 38368384, 2024). "GMCSF, IL-13, IL-1β, IL-2, IL-4, and IL-5 were undetectable in the vast majority of both TTP and COVID-19 samples." (PMID 39337495, 2024). "In parallel, patients with severe COVID-19 showed reduced concentrations of key Th2-related mediators (MDC, IL-5) and likely compensatory production of the anti-inflammatory mediator IL-10." (PMID 38368384, 2024). "COVID-19 exhibited a distinct immunological profile characterized by increased levels of Th1 (IL-12 and IFN-γ) and Th2 (IL-4, IL-5, IL-10, and IL-13) cytokines, along with IL-1β and IL-6, among other markers." (PMID 39408907, 2024). "Eosinophils' expansion and activation are stimulated by TH2 cytokines, especially IL-5, that correlated with SARS-CoV-2 clearance in COVID-19." (PMID 37383608, 2023). "However, it remains unknown whether vitamin D can affect COVID-19 severity by regulating IL-5." (PMID 37705107, 2023). "For example, increased IL-5, IL-6, IL-10, and MIG but deceased MIP-1β were observed in patients with severe/critical COVID-19 or those admitted to ICU, with satisfactory AUCs for predictive performance." (PMID 37469595, 2023). "In co-infected patients:↑ TNF-α, MIP-1β, and IL-9 compared with COVID-19-only.↑ TNF-α, IL-1β, IL-17A, IL-5, FGF-basic, and GM-CSFcompared with TB-only.↓ specific response to SARS-CoV-2 and Mtb." (PMID 37662901, 2023). "CCL22, IL-12/IL-23p40, IL-5, IL-17A and TNF-β levels, on the other hand, were greater in mild or moderate COVID-19 patients than in severe COVID-19 patients (P < 0.05)." (PMID 35958594, 2022). "Symptomatic COVID-19 patients had significantly (p < 0.05) higher levels of IL-10, IL-2, IL-2R, IL-6, IL-8 GM-CSF IP-10, TNF-α, IL-4, IL-5, IL-12, IFN-γ and MIP-1β compared to the asymptomatic cases." (PMID 36184636, 2022). "IL-6, IL-5, GCSF, IL-2, TNF-α, GMCSF, and IFN-γ were identified as COVID-19-related distinguishable cytokines, but only one (IL-12p70) was detected in the noninfected people." (PMID 35967091, 2022). "In the multiplex cytokine assays, plasma levels of Th2-related soluble factors such as IL-4, IL-5, IL-13, and CCL22 were comparable between the patient with COVID-19 mRNA vaccine-related myopericarditis and healthy controls." (PMID 35251049, 2022). "On the other hand, higher mean levels of IL-2 (p < 0.001) and IL-5 (p < 0.01) were produced by PHA-stimulated PBMCs from COVID-19 ICU patients compared to HC." (PMID 36363785, 2022). "In this study concentrations of TNF-α, IL-1b, IL-2, IL-4, IL-5, IL-6, IL-8, IL-10, IL-12 p70, GM-CSF, and IFN-γ were determined by a magnetic bead assay in tear film collected from 232 symptomatic COVID-19 patients." (PMID 35508669, 2022). "For example, the ratios of TNF-α/IL-5, IFN-α/IL-10, IL-6/IL-5, TNF-α/IL-4, and IFN- γ/IL-5, were lower (≈24-, 23-, 20-, 10-, and 10-fold) in COVID-19 ICU patients as compared with HC subjects." (PMID 36363785, 2022).
COVID-19 (continued). "Data analysis demonstrated an increased order of magnitude (≥3x) for CXCL8, CCL3, IL-6, IFN-γ, G-CSF and decreased order of magnitude (≤0.3x) for CCL11, IL-4, IL-5, IL-10, PDGF and IL-7 in COVID-19 patients throughout the kinetic follow-up." (PMID 36451835, 2022). "In contrast, COVID-19 ICU patients showed higher median levels of IL-2 (p < 0.001) and IL-5 (p < 0.01) by PBMCs." (PMID 36363785, 2022). "At baseline blood IL-1Ra, IL-5, IL-6, and TNF-alfa levels were significantly higher in COVID-19 compared to controls." (PMID 33767713, 2021). "In contrast, IL-1β, IL-4, IL-5, IL-12p70, IL-13, IL-17A, CCL11, and VEGF levels predicted severe COVID-19." (PMID 33995342, 2021). "Levels of pro-inflammatory (IFN-γ, IL-1β, IL-6, IL-9, IL-12p70, CCL11) and anti-inflammatory (IL-4, IL-5, IL-10, IL-13) cytokines, as well as VEGF, were higher in severely ill COVID-19 patients as compared to pandemic influenza A(H1N1) subjects." (PMID 33995342, 2021). "Meanwhile, COVID-19 displayed an immune profile distinguished by increased Th1 (IL-12, IFN-γ) and Th2 (IL-4, IL-5, IL-10, IL-13) cytokine levels, along with IL-1β, IL-6, CCL11, VEGF, TWEAK, TSLP, MMP-1, and MMP-3." (PMID 33995342, 2021). "In contrast, Th2 cytokines (IL-5 and MDC) and allergic inflammation-related cytokines (IL-5 and eotaxin) were reduced in patients with severe/critical COVID-19." (PMID 34938289, 2021). "The stimulation of PBMCs from COVID-19 patients with S protein peptides resulted in production of effector or Th1 cytokines (IFN-γ, TNF-α, and IL-2) and, to a lesser extent, Th2 (IL-5, IL-13, IL-9, and IL-10) and Th17 (IL-17A, IL-17F, and IL-22) cytokines." (PMID 32916812, 2020). "In our study, we found that the interleukins primarily involved in TEN were IL-4, IL-6, and IL-12, which were modulated (downregulated) by TEN, along with augmented IL-1α, IL-1β, IL-5, IL-8, NF-κβ, and interferons (IFN; α, β, and γ), which were modulated by COVID-19." (PMID 39941142, 2025). "However, there are limited data on the role of high IL-5 and IL-9 in PLWH/COVID-19 in COVID-19 outcome." (PMID 41516165, 2025). "Higher prepandemic concentrations of IL-2R, IL-4 and IL-5 protected against COVID-19, but not against SARS-CoV-2 infection." (PMID 40910046, 2025). "The presence of chronic inflammation in hypertensive patients may explain our observation of increased circulating levels of IL-4, IL-5, IL-13, IL-17A, and TNF-β levels during hospitalization in patients with COVID-19 and hypertension in the present study." (PMID 39685774, 2024). "Additionally, IL-2Rα, IL-5, IL-10, HGF, and IP-10 were correlated with SOFA scores in patients with severe-to-mild COVID-19 at different disease stages." (PMID 38710800, 2024). "In the COVID-19 context, it has been reported that serum IL-5 levels can be increased or not in patients with severe COVID-19." (PMID 38273281, 2024). "Comparing survivors and non-survivors, only IL-5 plasma levels were significantly increased in non-survivor COVID-19 patients (P=0.045)." (PMID 37207201, 2023). "Of interest, IL-5 plays a crucial role in our cohort being significantly different not only between HC and COVID-19 patients but also between non-survivor and survivor patients." (PMID 37207201, 2023). "We included in our tests a set of cytokines and chemokines with serum concentrations that were shown to increase during COVID-19, and this increase might also be reflected in breastmilk: TNF-α, IL-6, IFN-β, IL-1β, IFN-γ, IL-2, GM-CSF and IL-5, IP-10." (PMID 36560410, 2022). "Another immune signature detected in critically ill patients with COVID-19 includes the type 2 cytokines IL-4, IL-5, IL-13, and TSLP, related to noninfectious lung diseases (Choreño-Parra and others 2021)." (PMID 35647937, 2022). "On the other hand, serum levels of cytokines in COVID-19 ICU patients showed a significant increase in the production of GM-CSF, IFN-α, IL-2, IL-4, and IL-6 and a significant decrease in the levels of IFN-γ, IL-5, IL-12, IL-17A, and TNF-α." (PMID 36363785, 2022).
COVID-19 (continued). "Several mediators such as Tie-2, VEGFA, IL-17D, IL-3, GM-CSF, IL-1α, IL-5, Eotaxin 3, IL-12p70 and IL-13 were not significantly different between COVID-19 and control subjects (data not shown)." (PMID 36116160, 2022). "In addition, patients with COVID-19 had higher IFN-γ, IL-4, IL-5, and IL-6 concentrations compared to patients with influenza and higher IFN-γ and IL-10 concentrations compared to patients with bacterial CAP." (PMID 34987205, 2022). "Poddighe and Kovzel considered that patients with COVID-19 taking such agents (omalizumab, anti–IL-5 biologics, and dupilumab) had milder or even no symptoms." (PMID 36249911, 2022). "Our meta-analysis revealed significantly lower levels of immune cells (CD3+ T, CD4+ T, CD8+ T, B and NK cells), higher levels of cytokines (TNF-α, IL-5, IL-6 and IL-10) and higher levels of chemokines (MCP-1, IP-10 and eotaxin) in severe cases in comparison to mild cases of COVID-19." (PMID 34344353, 2021). "To investigate the role of cytokines and chemokines in the inflammatory status of COVID-19 and MIS-C, we measured plasma levels of IL-1ß, IL-2, IL-4, IL-5, IL-6, IL-10, TNF-α, IL-17A, IFN-α, IFN-γ, CXCL10/IP-10, CXCL8/IL-8, CXCL9/MIG, CCL5/RANTES, and CCL2/MCP1." (PMID 33841438, 2021). "Furthermore, COVID-19 convalescent individuals showed accompanying antigen peptide pools stimulated-IL-2 response, -IFN-γ response, and -IL-5 response." (PMID 34234102, 2021). "For example, IL-4 and IL-5 levels were not increased in wave 2 COVID-19 patients, suggesting lack of type 2 immunity activation." (PMID 34675240, 2021). "Later, during the advanced second phase of COVID-19, when the immune system starts slowing down viral replication, their antiviral properties are not requested, so IL-5 production is moderately reduced." (PMID 33767626, 2021). "Our synthesized results revealed significantly lower levels of immune cells in CD3+ T, CD4+ T, CD8+ T, B and NK cells, higher levels of cytokines (TNF-α, IL-5, IL-6 and IL-10) and higher levels of chemokines (MCP-1, IP-10 and eotaxin) in severe cases compared with mild cases of COVID-19." (PMID 34344353, 2021). "We have found fifteen cytokines that remain upregulated in convalescent COVID-19 individuals one month after infection (IL-1α, IL-3, IL-10, IL-12p70, CCL7, IFN-α2, bFGF, LIF, TRAIL, IL-2, IL-4, IL-5, IL-12p40, IL-17 and MIF) indicating a strong activation of the immune response." (PMID 34681885, 2021). "Cytokines related tissue repair, such as IL-10, IL-4, and IL-5, were also upregulated in COVID-19 patients, but without statistical significance between mild and severe patients." (PMID 32641700, 2020). "Moreover, the cytokines TNF, IL5, and IL10 have crucial roles in COVID-19 prognosis." (PMID 40766923, 2025). "The expression levels of a 13-cytokine panel (IL-1α, IL-1β, IL-2, IL-4, IL-5, IL-6, IL-8, IL-10, IL-12, NF-κβ, and IFN-α, IFN-β, and IFN-γ) were measured by qRT-PCR from peripheral blood mononuclear cells (PBMC) obtained from the patient with TEN and their parents (which were positive for COVID-19)." (PMID 39941142, 2025). "Additionally, IL-5 exhibited higher levels in the severe group across several visits, despite not frequently being reported as a marker for COVID-19 severity." (PMID 41166719, 2025). "In this group, we consistently observed strong correlations of IL-5 with IFN-γ and IL-1β with TNF-α, supporting the hypothesis of synergistic Th1 and Th2 responses and cooperative activity between type 1 and type 2 macrophages in controlling COVID-19." (PMID 37047752, 2023). "A significant increasing trend of IL-1β, IL-1ra, IL-2, IL-4, IL-5, IL-6, IL-7, IL-8, IL-10, IL-12(p70), IL-15, IL-17, FGF-b, G-CSF, GM-CSF, IFN-γ, IP-10, MCP-1, MIP-1α, PDGF, TNF-α, and VEGF was observed in the three groups (Controls ≤ Mild COVID-19 ≤ Severe COVID-19)." (PMID 34675240, 2021).